MUC20 (mucin 20, cell surface associated)
Diseases named in the same sentence as MUC20 in open-access papers (continued):
Sharing a sentence is not in itself a finding about the gene and the disease.
thyroid cancer (1 paper, 2020). "Moreover, MUC20 exhibited significantly high expression in dedifferentiated thyroid cancer cells." (PMID 33489878, 2020). "Thus, miR-146b-3p potentially targets MUC20 participation in the formation of DTC dedifferentiation, resulting in resistance to 131I and the loss of the iodine uptake ability of DTC cancer foci, promoting refractory differentiated thyroid cancer." (PMID 33489878, 2020). "Consequently, we suspect that the miR-146b-3p/MUC20/MET signaling pathway the targeting relationship of might play a role in the redifferentiation of iodine-refractory thyroid cancer." (PMID 33489878, 2020). "At present, there have been no reports regarding MUC20 in dedifferentiated thyroid cancer." (PMID 33489878, 2020). "In conclusion, our present findings show that anti-miR-146b-3p could restore radioiodine uptake in dedifferentiated thyroid cancer by up-regulating NIS expression and translocation to the cell membrane in vitro by targeting MUC20 through MET Signaling pathways." (PMID 33489878, 2020). "Therefore, it indicated that miR-146b-3p/MUC20/MET pathways may play important role in NIS expression and radioiodide uptake by inhibition of miR-146b-3p expression to induce redifferentiation of dedifferentiated thyroid cancer cells." (PMID 33489878, 2020).
tumor (20 papers, 2013 to 2024). "Many mucins were abnormally expressed in adenocarcinomas and were associated with carcinogenesis, tumor invasion, and prognosis and we selected MUC20 (fold change =1.577, P = 0.005) as a newly recognized biomarker to investigate its role in CRC." (PMID 23787019, 2013). "Among these genes, PED4FIP and MUC20 were noted as frequently mutated in malignant tumors and play a role in tissue damage repair and tumor growth through activation of the HGF‐MET pathway, and some evidence suggests that their mutation and expression levels correlate with prognosis." (PMID 37649308, 2023). "MUC20 is a molecule involved in mucin production and has been reported to play a tumor-promoting role in gastrointestinal cancer and gynecological cancer." (PMID 35330413, 2022). "More recently, some studies have suggested a relationship between MUC20 and tumour pathobiology in other model systems." (PMID 34651428, 2021). "Since MUC2 is a tumour suppressor, whereas overexpression of MUC20 favours tumour progression, these data indicate that BAs facilitate tumour development under normal conditions, by altering the expression of these mucins." (PMID 33328627, 2020). "In intraperitoneal, subcutaneous, and orthotopic injection models, MUC20 knockdown decreased tumour growth in immunodeficient mice." (PMID 29993037, 2018). "Immunohistochemistry (IHC) revealed the weak expression of MUC20 in pancreatic ductal cells in non-tumour regions." (PMID 29993037, 2018). "Immunohistochemistry confirmed that the higher MUC20 expression was observed in excised control tumour than that in MUC20 knockdown tumour (P = 0.00178)." (PMID 29993037, 2018). "MUC20 knockdown tumours were smaller and weighed less than control tumours for both HPAC (P = 0.0244) and HPAF-II cells (P = 0.0233)." (PMID 29993037, 2018). "The results demonstrated that MUC4 and MUC20 were expressed at low levels in the tumor tissue samples obtained from chemosensitive patients (TRG1/2/3), whereas the expression of MUC13 did not significantly correlate with TRG." (PMID 26673820, 2016). "Patients with low expression of MUC4 or MUC20 would have a good tumor regression and fewer residual cancer cells." (PMID 26673820, 2016). "The MUC20‐OE mice had significantly lower tumour weight and volume compared with the other mice." (PMID 34651428, 2021). "However, in the xenograft model, tumour growth was somewhat slower in MUC20‐OE mice than in CR models." (PMID 34651428, 2021). "Furthermore, there were six genes (EGR1, MUC20, MUC3A, NBPF19, NOL4L, and OR4L1) that were simultaneously mutated in the tumor tissues and junction tissues." (PMID 33133167, 2020). "Moreover, MUC20 knockdown decreased tumour formation after four weeks of orthotopic injection with HPAF-II cells in NOD/SCID mice." (PMID 29993037, 2018). "MUC4, MUC16 and MUC20 mRNA expression was evaluated in datasets to analyze whether the mRNA level differed between normal and tumor tissues." (PMID 30236127, 2018). "In addition, this study proves that MUC20 expression is upregulated in PDAC tissues compared with that in non-tumour pancreas tissues, and that the high expression of MUC20 correlates with poor survival." (PMID 29993037, 2018). "MUC16 and MUC20 mRNA level were also increased (p < 0.0001 and p = 0.0062) in tumor samples." (PMID 30236127, 2018). "MUC20 knockdown decreases PDAC tumour growth in immunodeficient mouse models." (PMID 29993037, 2018). "Furthermore, MUC20 knockdown inhibits tumour cell growth both in vitro and in vivo." (PMID 29993037, 2018).
tumor (continued). "MUC20 inhibits the lactylation of MET, thereby reducing tumor cell resistance to proteasome inhibitors, indicating a role for lactylation in the development of drug resistance in tumor cells." (PMID 39010066, 2024). "Since MUC20 upregulation is known to support tumour development and MUC 2 is a tumour suppressor, this study’s results suggest that BA aids tumour progression under normal conditions." (PMID 37509236, 2023). "A MUC20 -lncRNA has been reported to bind ROCK1 and to be functionally involved in tumor suppression indicating trans-regulation." (PMID 34194481, 2021). "Specifically, three membrane‐bound MUCINs (MUC3A, MUC12, and MUC20) and one atypical mucin (MCAM) were overexpressed in the tumor samples (p < 0.05)." (PMID 34327857, 2021). "In the subcutaneous injection model, MUC20 knockdown decreased the sizes and weights of HPAF-II tumour cells compared with the control group in NOD/SCID mice (P = 0.0082)." (PMID 29993037, 2018). "IHC was conducted to examine the expression of selected target markers MUC4, MUC13, and MUC20 in 186 ESCC resection samples and the relationships between their expression and tumor regression grade was analyzed." (PMID 26673820, 2016). "In conclusion, MUC20 is frequently up-regulated in PDAC tumours compared with non-tumour pancreas tissue, and MUC20 high expression correlates with poor prognosis of patients." (PMID 29993037, 2018). "MUC20 expression was not modified by CFZ therapy in MUC20‐overexpressing tumours." (PMID 34651428, 2021).
cancer (16 papers, 2016 to 2024). A tumor composed of atypical neoplastic, often pleomorphic cells that invade other tissues. "Co-expression network showed genes closely associated with RAC1 were calculated among which cancer genes such as MUC1, MUC20, CEACAM5, andCCL20 were positively correlated to expression of RAC1 whereas TIMP3 and MGP was negatively correlated." (PMID 37202394, 2023). "MUC20 can contribute to cancer progression since hypoxia and low pH upregulate MUC20 expression that is able to physically interact with the MET receptor, being a crucial mediator between PSCs and cancer cell communication." (PMID 35711414, 2022). "MUC20 is over-expressed in many cancers, and has been shown to regulate cell growth, differentiation, metastasis, adhesion, and invasive immune surveillance." (PMID 33489878, 2020). "We selected 6 genes (MUC4, MUC13, MUC20, BMP7, AKT3, and SMAD3) that were closely associated with the development and progression of cancer to validate the conclusions drawn from the gene expression profiling analysis." (PMID 26673820, 2016). "Several studies have shown that MUC20 is involved in drug resistance in different cancers." (PMID 38439082, 2024). "Therefore, our study revealed for the first time the mechanism by which MUC20 regulates drug resistance in cancers via a novel PCD (cuproptosis)." (PMID 38439082, 2024). "According to these data, the expression patterns of these genes either increased or decreased in different cancer cell lines, and some of the genes, including MUC20 and B4GALNT3, showed decreased expression in HCC cell lines compared to other cancer cell lines." (PMID 36556285, 2022). "MUC20 is also an independent prognostic factor for the poor survival rate of malignant tumors." (PMID 33489878, 2020). "MUC20, FZD10 have been identified in PC patients and these two genes play a vital role in two important pathways associated with cancer." (PMID 33240632, 2020). "We also analyzed MUC4, MUC16 and MUC20 expression in datasets of other cancers." (PMID 30236127, 2018). "A recent study of mucin expression in a human epithelial carcinoma cell line (A549) showed a strong induction of MUC8, MUC15, MUC20, MUC21, and MUC22 mediated by RSV infection." (PMID 29162850, 2017). "However, MUC12, MUC15, MUC17, and MUC20 had a significant increase in methylation in only KIRP and KIRC, which goes against the overall observed demethylation of mucins in the cancers examined here." (PMID 28978023, 2017). "However, the glycosylation differences of MUC15 and MUC20 between the cancer and normal cells were not fully explored." (PMID 36482940, 2022). "However, whether MUC20 regulates drug resistance in cancer by modulating PCD has not been reported." (PMID 38439082, 2024). "For MUC12, MUC17, MUC20 and MUC22, no statistical differences between cancer samples and normal controls were observed." (PMID 34828282, 2021).
infection (10 papers, 2011 to 2023). The state of being infected such as from the introduction of a foreign agent such as serum, vaccine, antigenic substance or organism. "BALB/c mice were infected with HMPV, and the expression of Muc1, Muc2, Muc4, Muc5ac, Muc5b, Muc15, Muc16, Muc19, and Muc20 were analyzed at 12, 24 and 48 h after infection." (PMID 32899224, 2020). "Secondly, we assessed the relative effects of ITGB5 and MUC13 on mRNA expression of the two mucin genes (MUC4 and MUC20) in response to 3 h infection with ETEC strain 200 (MOI = 8∶1) at 44 h after siRNAs transfection." (PMID 23922972, 2013). "In contrast, G5P infection decreased expression of transmembrane mucin genes significantly (MUC12, MUC16 and MUC21) or numerically (MUC1, MUC4, MUC13 and MUC20)." (PMID 37848925, 2023). "Among the membrane bound and secreted mucins tested, MUC1, MUC20 and MUC6 transcription levels were observed to increase during the infection." (PMID 21569362, 2011). "Our data indicate that the MUC expression by RSV and hMPV differs significantly, as we observed a stronger induction of MUC8, MUC15, MUC20, MUC21, and MUC22 by RSV infection while the expression of MUC1, MUC2, and MUC5B was dominated by the infection with hMPV." (PMID 25977598, 2015). "No major changes were observed in Muc1, Muc15 and Muc20 levels during chronic or acute infection when compared to uninfected control mice (day 21 pi." (PMID 21155842, 2011). "Increased gene expression of MUC1, MUC6 and MUC20 was observed, while MUC5AC did not change during infection." (PMID 21569362, 2011). "Compared to uninfected cells, HMPV infection induced a significant fold-increase expression of MUC1 (8.3 ± 2), MUC2 (43.4 ± 13), MUC4 (54 ± 12), MUC5ac (23.3 ± 11.5) and MUC19 (77 ± 35), while no significant induction of MUC15, MUC16 and MUC20 was observed." (PMID 32899224, 2020).
adenocarcinoma (3 papers, 2013 to 2020). A common cancer characterized by the presence of malignant glandular cells. "In contrast, MUC20 was expressed on the apical surface and cytoplasm of adenocarcinoma cells." (PMID 29993037, 2018).
MUC20 also shares sentences with these, for which no sentence is quoted: Obesity (2 papers); pulmonary fibrosis (2); bladder cancer (1); colitis (1); colon cancer (1); Hypertension (1); lung disease (1); monoclonal gammopathy of undetermined significance (1); mucinous colorectal adenocarcinoma (1); renal fibrosis (1); stomach cancers (1); type 1 diabetes (1).